CRP (C-reactive protein)
Diseases named in the same sentence as CRP in open-access papers (continued):
Sharing a sentence is not in itself a finding about the gene and the disease.
infection (continued). "In some cases, this might take up to 60 days and thus higher CRP values may be present during this time in the absence of infection." (PMID 36289943, 2022). "Although the cause of this phenomenon is undeciphered, discrepancies in the levels of acute phase reactants such as C-Reactive Protein following the administration of TCZ, which might mask the typical signs of infection and therefore delay diagnosis have been previously reported." (PMID 36131317, 2022). "Interestingly, CRP, AAT, and SLPI specifically inhibit the ATP (trauma)-induced release of IL-1β, while sparing the ATP-independent inflammasome activation against pathogens, which is vital in the context of severe injuries and infections." (PMID 36105198, 2022). "Additionally, the elevation of CRP in newborn infants is not specific to infection, as observed following maternal fever, birth asphyxia, and meconium aspiration." (PMID 36501194, 2022). "A low POC CRP as a standalone tool did not seem to be sufficient to rule out serious infections, but its potential in assessing serious infections could increase when integrated in a clinical decision rule." (PMID 36333682, 2022). "Laboratory results demonstrated white blood cell count 6,300/μL (normal: 4,000–11,000/μL), C-reactive protein (CRP) 36 mg/L (normal: <10 mg/L), erythrocyte sedimentation rate (ESR) 90 mm/Hr (normal: <20 mm/Hr), and procalcitonin 1.6 ng/mL (normal: <0.5 ng/mL), compatible with infection." (PMID 35223115, 2022). "We also could not use other inflammatory markers such as CRP or procalcitonin to exclude patients with ongoing infection." (PMID 35109827, 2022). "ESR and CRP values were checked for all patients to rule out subclinical infection." (PMID 35602781, 2022). "Screening of high-risk individuals could comprise of a thorough history, clinical examination, blood test panel (C-reactive protein, troponin, B-type natriuretic peptide/NT-proBNP, glycated haemoglobin, lipids), ECG, and transthoracic echocardiography at least 8–12 weeks from infection." (PMID 35176758, 2022). "The decrease in the TAU group after receiving standard measures appears to be greater (−2.2 ± 2.5 mg/l, n = 6) due to the fact that the baseline value contains two outliers with singularly elevated CRP values (5.8 mg/l and 5.5 mg/l) without clinical signs of infection." (PMID 34297188, 2022). "The levels of PCT, CRP, and D-dimer were significantly elevated in patients with positive blood culture results (patients with infection) compared to those in the patients without infection." (PMID 36148158, 2022). "Elevated C-reactive protein levels over a threshold of 1.5 mg/dL were highly predictive of short-term mortality in a time window of 30–90 days post-intervention, even in the absence of infection or a requirement for antibiotic therapy." (PMID 35625755, 2022). "However, approximately 35–65% of hospitalized newborn infants are CRP-negative when the first clinical symptom suggestive of a serious infection is noted." (PMID 36501194, 2022). "In addition, the CRP cutoff of 100 mg/dl was retrospectively determined by optimizing the Youden’s analysis of ROC data and the choice of day 2 was arbitrary to minimize the influence of ICU-acquired infections." (PMID 35618852, 2022). "None of the widespread laboratory markers of infection [C reactive protein (CRP), white blood cell count (WBC), absolute neutrophil count (ANC), immature to total neutrophil ratio (IT-ratio)] has enough sensitivity or specificity to detect all infected children." (PMID 35345614, 2022). "Based on this experience, we would recommend that in patients presenting with increased D-dimers, reduced platelet counts, and an elevated INR without an increased C-reactive protein or other signs of infection, KHE should be considered as a differential diagnosis." (PMID 36551267, 2022).
infection (continued). "Moreover, in seven patients, there was a noticeably significant postoperative increase in CRP, most likely an expression of inflammation following surgical trauma rather than infection." (PMID 35203403, 2022). "Regardless, even with placement of stabilizing hardware, the patient adequately eradicated his infection as suggested by his lack of wound complications, normal postoperative C-reactive protein and erythrocyte sedimentation rate, and lack of systemic signs of infection." (PMID 36227832, 2022). "We therefore analyzed CRP and WBC count progress over the course of 14 days after the first stage of TSR, in addition to singular values, to see if the count progress is a better indicator for determining infection status than the singular value before reimplantation alone." (PMID 36671215, 2022). "The combination of frequently tested peripheral blood parameters (such as CRP, HGB, eosinophil, monocyte, and lymphocyte levels) can differentiate between children with and without acute infection, and provide a relatively sensitive and specific indication of the infection type." (PMID 36095013, 2022). "CRP was a non-specific marker of inflammation, which could rapidly increase within 4–6 h of infection." (PMID 35498793, 2022). "Increased CRP levels suggest a developing infection, but the results are not specific." (PMID 35884890, 2022). "Finally, CRP and albumin, and thereby GPS, could have beeninfluenced by other factors, ie, infection, inflammation, comorbidity, nutrition,and medication (eg, corticosteroids), but our study was not designed to collect suchdata." (PMID 35342321, 2022). "In our study, CRP had the highest sensitivity of 79.6% and specificity of 88.8% on POD 6, with an AUC of 0.88, which was higher than that of presepsin, suggesting that CRP might be better at detecting postoperative infections in colorectal surgery." (PMID 35273185, 2022). "However, there are researches finding that the mechanism of POCD is related to inflammatory response, CRP serves as a marker of non-specific acute-phase response in inflammation, infection, and tissue damage, related to the development of POCD." (PMID 36186818, 2022). "At diagnosis, he presented with fever and a CRP of 69.7 mg/L without a focus of infection." (PMID 36440328, 2022). "In addition to CRP, PCT is also commonly used in clinical practices as an infection indicator." (PMID 36443747, 2022). "Furthermore, the mean CRP values of reinfection and infection-free groups were found to be not statistically significantly different (p = 0.69)." (PMID 36139954, 2022). "It is a known fact that the not infection-related elevation of plasma CRP levels may mark systemic cardiac stress response and have a prognostic role in HF." (PMID 35409075, 2022). "In comparison to other biomarkers like CRP and IL-6, which have inadequate sensitivities at different stages of an illness, SAA was found to be a reliable screening sign for the first 24 hours following infection start, thus raising its potential relevance as a biomarker." (PMID 35449688, 2022). "A negative CRP at that time was viewed as a ruled-out infection." (PMID 36233706, 2022). "CRP and ESR could be considered as infection indicators of infection." (PMID 36299571, 2022). "However, in contrast to our results, they found that CRP was not an independent predictor of neurological outcome after correction for concomitant infection." (PMID 35618852, 2022). "In addition to expression during infection, CRP has reportedly been raised in patients with non-infectious diseases including rheumatoid arthritis." (PMID 35884890, 2022). "Notably, the weaknesses in this study’s design which are likely to have skewed the CRP result also apply to the EDPs, and further assessment in a broader sample (without pre-selection for clinical evidence of infection) is needed." (PMID 35176042, 2022).
infection (continued). "Increased NE ratio, CRP, ESR, and PCT levels were discovered in most of patients, consistent with the previous study, suggesting these inflammatory biomarkers may contribute to assessing the infection of C. psittaci." (PMID 35816485, 2022). "P-SEP, when combined with IL-6 and CRP, may be utilized as a negative predictive marker of EOS (NPV 97.2%, 95% CI: 93.3–101), especially in newborns at low to medium risk of infection." (PMID 36699313, 2022). "Therefore, continuously observation of CRP and ESR after PLIF can accurately determine whether infection occurs, which is conducive to timely detection and treatment of infection." (PMID 36684362, 2022). "Inflammation is the body's physiological response to injury, illness, infection, or environmental insult, and is characterized by the presence of proinflammatory cytokines and acute-phase proteins (APP), such as C-reactive protein (CRP) and α-1-acid glycoprotein (AGP)." (PMID 36475018, 2022). "In addition, CRP and PCT have been employed as inflammation-related infection biomarkers." (PMID 36588684, 2022). "In the group without serious infection, median CRP was 10 mg/L (IQR < 5–27)." (PMID 36333682, 2022). "For this reason, diagnoses of infections relying on the detection of CRP are not accurate." (PMID 35144683, 2022). "CRP is an acute phase reactant synthesized in the liver but is not a specific marker of infection." (PMID 33857241, 2021). "The positive correlation between RDW and CRP in the absence of an association between RDW and early infection, suggests that RDW may indeed be a marker of baseline chronic inflammation." (PMID 32959199, 2021). "However, these patients presented with analytical findings of infection (e.g., elevated C-reactive protein or procalcitonin, significant leucocytosis) in absence of other infectious origin, which would be absent in the latter." (PMID 34099754, 2021). "Moreover, the infection-related biomarkers including ferritin, CRP and procalcitonin also exhibited higher levels in non-survivors." (PMID 34521370, 2021). "High CRP on POD 3 might reflect systemic inflammation and concomitant infection." (PMID 34082725, 2021). "In conclusion, this study indicates that at the initial stage of SARS-CoV-2 and SFTS infection, the blood indices of patients are distinct from each other, including WBC count, absolute LYMPH count, PLT count, absolute CD4+ T cells count, and IL-6, TNF-α, D-D, CRP and FIB levels." (PMID 34238962, 2021). "Meanwhile, the recent infectious indicators of patients, such as white blood cell count (WBC), neutrophil percentage (NEU%), high-sensitivity C-reactive protein (hs-CRP), procalcitonin (PCT), among others, were also taken into consideration to determine whether patients had symptoms of infection." (PMID 34778288, 2021). "Oxyhemoglobin saturation and oxygenation index decreased, and C-reactive protein (CRP) and serum amyloid A (SAA) levels were elevated in all patients with COVID-19 infection, with statistically significant differences between those with severe disease and mild infection (all P < 0.05)." (PMID 33627079, 2021). "Given good discrimination by CRP kinetics among patients presenting with relatively low CRP values, which are not indicative of infection type, could help in avoiding misuse of antibiotics." (PMID 34863104, 2021). "There was also no change in calibre when individuals with infections were treated with antibiotics but their CRP levels did not fall below 100 mg/L. The reduction in venular calibre thus appeared to reflect the decrease in CRP level." (PMID 34446820, 2021). "However, in this case, there were no signs of infection because the white blood cell count and CRP and ESR levels of the patient were normal." (PMID 34330332, 2021).
infection (continued). "To further confirm the relationship between H3K18la with infection, we compared expression of H3K18la with clinical biomarkers of infection, including WBC, neutrophil count, neutrophil percentage, lymphocyte count, lymphocyte percentage, monocyte count, monocyte percentage, PCT and CRP levels." (PMID 35069560, 2021). "In addition to CRP, the abnormal peak located around the 37fL channel in the WBC histogram can provide a good estimation of the number of large parasites present during the infection." (PMID 34565334, 2021). "Autoinflammatory complications were described either as well-defined autoinflammatory diseases (AD) or undifferentiated “autoinflammatory disease” (UAD) (defined as CRP over 10.0 mg/L on five consecutive occasions, taken at separate times and not explained by infection)." (PMID 33679746, 2021). "The symptoms of SAT may be assigned to the infection, as neck pain (if present) may be referred to throat or lymph nodes involvement, while fever, fatigue, and increased inflammatory markers (CRP, WBC) may further confirm the false negative diagnosis." (PMID 33950404, 2021). "In this context, we acknowledge that altered serum CRP levels may be affected by factors not discussed in this study such as infection or immune disease." (PMID 34154662, 2021). "Conversely, CRP and PCT had limited value to discriminate neonates with the most severe clinical courses already at T0, with a limited utility of PCT for the early discrimination of patients subsequently developing septic shock (AUC septic shock vs. infection 0.65, 95% CI: 0.504–0.795)." (PMID 34068959, 2021). "Moreover, an increased CRP level indicates a general inflammation without pointing towards a specific infection nor a specific wound, if the patient for example has multiple wounds." (PMID 35011910, 2021). "Clinical manifestations, the time required for the cerebrospinal fluid (CSF), blood culture, nonspecific infection markers such as platelets and C-reactive protein (CRP) to turn normal, and drug-related side effects were observed and recorded in the process of treatment." (PMID 34248616, 2021). "Furthermore, the low-TT group of the present study exhibited elevated levels of C-reactive protein, a classic inflammatory indicator, in the absence of infection." (PMID 34872528, 2021). "Thirteen of 134 patients without infection and two of 40 infected patients had no CRP test ordered." (PMID 34546893, 2021). "However, the CRP concentration of 150 μg/ml used in the immunofluorescence imaging and flow cytometry experiments is not unusual and can be achieved in case of infections but also non-infectious inflammatory lesions, as reported in." (PMID 34899688, 2021). "In dogs with acute CME, CRP concentrations were reported to increase dramatically between days 4 and 16, peaking at 1-6 weeks after inoculation with E. canis in dogs; similarly, most dogs with chronic CME from natural infection presented an increase of CRP levels." (PMID 34840450, 2021). "However, the leukocyte count and the C-reactive protein level in the enrolled patients were much above the upper normal limits, which indicated that most of the enrolled patients had infection rather than colonization." (PMID 34330333, 2021). "Interestingly, ESR and CRP were still relatively high 2 weeks after surgery and were not different between the two groups before infection started (p = 0.12 and 0.4, respectively)." (PMID 33256763, 2020). "And the indicators of infection such as CRP, ESR and T-SPOT were negative." (PMID 32948151, 2020). "Although CRP has a sensitivity of 71.4% and specificity of 100% for active disease in a study, CRP may elevate nonspecifically in tissue inflammation and infection, so it may not accurately reflect the disease status." (PMID 33303010, 2020). "Serum CRP might here be a poor indicator of chronic PJI because a systemic inflammatory response could be absent during infection with low-virulent microorganisms." (PMID 33266181, 2020).
infection (continued). "Third, the study had maternal CRP measurement at only one time point in early pregnancy and thus the lack of findings seen may not be applicable to infections and inflammation occurring later during pregnancy." (PMID 31312974, 2020). "Furthermore, C-reactive protein, a marker of inflammation, was not measured and therefore it cannot be ensured that SF was not confounded by infection, inflammation, or injury, however, all participants reported to be in good health at the time of testing." (PMID 32850940, 2020). "With regard to percent changes for determining the timing of reimplantation, the AUC indicated that percent changes in the CRP (AUC = 0.464), the IL-6 (AUC = 0.534), the ESR (AUC = 0.527), and the fibrinogen (AUC = 0.586) were all poor markers when predicted persistent or recurrent infection." (PMID 32887615, 2020). "However, cirrhotic patients show a reduced increase in their CRP levels during infection compared with noncirrhotic patients." (PMID 33198109, 2020). "In addition, international risk models for the assessment of severity of infection are scarce and neither the common infection parameter CRP nor the highly sensitive PCT can reliably differentiate between neutropenic infections and chemotherapy-induced fever." (PMID 32519027, 2020). "Previous studies have highlighted that low-grade infections might not result in elevated CRP or IL-6; however, due to limited numbers these findings should be evaluated for specific organism in future studies." (PMID 32927683, 2020). "However, the normalized leukocyte count and CRP became negative with antibiotic therapy indicating that the infection was cleared." (PMID 33384740, 2020). "CRP (AUC 0.520, 95% confidence interval, 0.382–0.659) had a significantly lower AUC value than of both PCT (AUC 0.773, 95% confidence interval, 0.661–0.886; P = 0.0056) and WBC (AUC 0.739, 95% confidence interval, 0.624–0.853; P = 0.017) for distinguishing HAdV-7 from HAdV-3 infection." (PMID 33145348, 2020). "Nevertheless, despite the well-documented regulatory pathways of infection and inflammation on iron regulation, it is important to note that multiple publications have shown a lack of correlation between hepcidin, IL-6, and C-reactive protein (CRP) in sick neonates." (PMID 32793848, 2020). "Without infection, CRP levels are higher in active SLE than in inactive SLE18,28." (PMID 33199770, 2020). "Compared to healthy controls, SC-CIP patients had higher biomarkers of gut permeability (DAO), systemic inflammation (CRP) and bacterial translocation (sCD14), although none of the patients had clinically apparent signs of infection when the samples were taken." (PMID 32906634, 2020). "We hypothesize that in individuals in whom the conformation of CRP remains unchanged, perhaps due to inappropriate inflammatory conditions around CRP, CRP is not fully functional during infection." (PMID 33117400, 2020). "Although CRP level is well-correlated with systemic inflammation and could be used to detect SIRS progression, there could be false positive results in the early-phase of infection or in immunocompromised hosts." (PMID 32709867, 2020). "However, there is no reliable evidence yet to suggest that low or decreasing CRP values indicate the elimination of infection." (PMID 32089975, 2020). "A protocol based on daily monitoring of CRP levels may support a tailored time of antibiotic therapy in critically ill patients in a single infection episode, but without reducing the total exposure of these patients to antimicrobials." (PMID 32487263, 2020). "The infection is not considered initially because patients have no clinical or laboratory signs of severe bacterial infection, such as fever, leucocytosis with left-shift, elevated C-reactive protein and procalcitonin levels." (PMID 33137889, 2020). "Unlike WT CRP, both E-CRP-1 and E-CRP-2 were protective against late-stage infection." (PMID 33117400, 2020).